MGMT (O-6-methylguanine-DNA methyltransferase)
Diseases named in the same sentence as MGMT in open-access papers (continued):
Sharing a sentence is not in itself a finding about the gene and the disease.
glioma (continued). "The classical molecular markers IDH, 1p/19q, and MGMT status have long been used to evaluate clinical strategies and prognosis in patients with glioma." (PMID 39492838, 2024). "Studies have shown a positive effect of proven methylation of the MGMT promoter in patients with high-grade glioma on the overall prognosis." (PMID 38674026, 2024). "TMZ, an alkylating agent, has clear anti-tumor activity as a monotherapy in treating gliomas, particularly effective in gliomas with low expression of MGMT (methylguanine-DNA methyltransferase)." (PMID 39039049, 2024). "Another group of researchers synthesized a matrix metalloproteinase (MMP)-responsive hydrogel to target the overexpression of O6-methylguanine-DNA methyltransferase (MGMT) by glioma cells." (PMID 39057463, 2024). "This study aims to assess the potential of Visually AcceSAble Rembrandt Images (VASARI) MRI features to predict glioma characteristics such as grade, IDH mutation, and MGMT methylation status." (PMID 38167551, 2024). "Patients with glioma exhibit a diverse array of genetic mutations, including IDH1 mutation, MGMT promoter methylation, and 1p/19q co-deletion." (PMID 39574472, 2024). "Remarkably, both ADAM10 G342E (score = −0,81) and ADAM15 N792S (score −1,1) missense pathogenic mutation were associated to low grade glioma, methylated MGMT promoter status and mutant IDH status, which correspond to a positive prognosis in glioma patients." (PMID 38272115, 2024). "Previous studies have employed machine learning algorithms to predict glioma grades and molecular markers like IDH mutation status and MGMT methylation." (PMID 39100020, 2024). "Previous studies have identified biomarkers such as 1p/19q codeletion, isocitrate dehydrogenase, EGFR, and O6-methylguanine-DNA methyltransferase (MGMT) gene promoter methylation as indicators for gliomas." (PMID 38613802, 2024). "Temozolomide is the most common and effective chemotherapy drug for malignant glioma patients, but the efficacy of alkylating agents such as TMZ is related to the methylation status of the O6-methylguanine-DNA methyltransferase (MGMT) promoter in gliomas." (PMID 38967893, 2024). "Our study offers valuable insights into the potential application of MRI-based VASARI features for non-invasively predicting glioma grade, IDH mutation status, and MGMT methylation status." (PMID 38167551, 2024). "One study found that MRI features, such as the proportion of enhancing and non-enhancing tumors, the amount of restricted diffusion, and the proportion of edema, significantly varied between gliomas with methylated MGMT versus unmethylated MGMT." (PMID 39100020, 2024). "We also evaluate the performance of multiple machine learning models in predicting glioma grade, IDH mutation status, and MGMT methylation, as well as identify which VASARI features hold the most predictive power in these models." (PMID 39100020, 2024). "Current research on AI-assisted prediction of MGMT promoter methylation in glioma mainly focuses on radiomics." (PMID 38385046, 2024). "In this study, we employed four distinct machine-learning models to classify glioma grade, IDH mutation, and MGMT methylation based on VASARI features." (PMID 39100020, 2024). "MGMT promoter unmethylated gliomas exhibited higher MTR3.5 signals compared to MGMT promoter methylated gliomas (mean: 0.01 vs -0.01, p = 0.048)." (PMID 39759149, 2024). "In clinical practice, the combination of the 1p/19q co-deletion and MGMT promoter methylation is considered the “gold standard” for assessing the sensitivity of gliomas to TMZ." (PMID 39574472, 2024). "All interactions involving IDH1 and MGMT were included to highlight connections relevant to glioma biology." (PMID 39767713, 2024). "Serum MGMT expression and CPTAC notably overlapped with respect to CTSA (upregulated in glioma and associated with immune infiltration), MTFHD1 (one-carbon metabolism association in GBM), and CD320 (implicated in a cobalmin-mediated metabolism)." (PMID 38612892, 2024).
glioma (continued). "Radiomics models have been developed to predict genetic features like MGMT methylation and EGFR-A289V mutations in high-grade gliomas and ATRX mutations in lower-grade gliomas (LGGs)." (PMID 38927583, 2024). "Their suggested pipeline reduced inter-observer variation in glioma segmentation, sped the tumour annotation process, and accurately predicted the MGMT methylation status." (PMID 38291266, 2024). "For this reason, it is crucial to assess the efficacy of drugs against glioma cells with diverse molecular backgrounds with various MGMT promoter methylation statuses." (PMID 39682123, 2024). "Within the TCGA database, CLEC7A demonstrated elevated expression in samples of high-grade gliomas, MGMT un-methylated status, IDH wildtype status, and those 1p/19q no-codel status." (PMID 38846954, 2024). "The patients with glial tumors were classified using conventional tests (codeletion 1p/19q (FISH), Mutation IDH (IHQ), MGMT promoter methylation (PCR)), and genomic sequencing using the FoundationOne®CDx (F1CDx) and FoundationONE Liquid CDx (F1LCDx) panels." (PMID 39767683, 2024). "In the context of ATRi plus temozolomide combination treatment, the MGMT status had been previously defined as a predictive factor for synergistic combination of ATRi plus temozolomide in glioma cells." (PMID 38475864, 2024). "This review aimed to evaluate the quality of prior studies on predicting MGMT methylation status in gliomas based on MRI-radiomic features, using the RQS items." (PMID 38308012, 2024). "In clinical practice, the methylation status of the MGMT promoter has been affirmed as a prognostic indicator, pivotal in forecasting the sensitivity of patients with glioma to temozolomide, as well as predicting their subsequent clinical outcomes." (PMID 39286478, 2024). "MGMT immunohistochemistry expression has revealed substantial correlations with diverse glioma grades and subtypes, including lymphomas, thymic tumors, and pituitary tumors." (PMID 38255825, 2024). "In another study, patients with newly diagnosed MGMT unmethylated glioma were tested for the effectiveness of nivolumab with RT vs. standard chemoradiotherapy." (PMID 39452154, 2024). "The role of sex in differentially impacting the survival benefit of MGMT methylation status in gliomas is being increasingly recognized." (PMID 38611052, 2024). "The dose density scheme is to regenerate the cytotoxic effects of TMZ in drug-resistant glioma by depleting MGMT activity in blood monocytes at a continuous low dose." (PMID 38733690, 2024). "Our results also show for the first time that PU-H71 can overcome inter-tumor heterogeneity and be used against glioma cells with varied molecular backgrounds and differing MGMT promoter methylation statuses." (PMID 39682123, 2024). "PubMed Medline, EMBASE, and Web of Science were searched to identify MRI-based radiomic studies on MGMT methylation in gliomas published until December 31, 2022." (PMID 38308012, 2024). "In a different investigation, the capacity to decrease MGMT expression in glioma cells was assessed in regards to rutin, catechin, dehydrozingerone, naringenin, and quercetin treatment, both individually and in combination with TMZ." (PMID 38611962, 2024). "Few studies have discovered a relationship between gliomas crossing hemispheres and MGMT methylation." (PMID 38167551, 2024). "Preoperative determination of MGMT promoter methylation status is important to optimize treatment strategies for patients with gliomas." (PMID 39272871, 2024). "For example, exosomes released by reactive astrocyte (RAS) were used to deliver O6-methylguanine DNA methyltransferase (MGMT) mRNA to MGMT-negative glioma cells, effectively overcoming the temozolomide resistance." (PMID 38164145, 2024). "Together, these results suggest that MGMT protein plays a role in the radioresponse of both glioma and melanoma cell lines." (PMID 38811596, 2024).
glioma (continued). "Multiple genetic alterations in glioma tissues, such as IDH1 mutations, 1p/19q co-deletion, and MGMT promoter methylation, serve as significant indicators of prognosis and drug responsiveness." (PMID 39574472, 2024). "Regarding the methylation status of the promoter of the MGMT gene (O6-methylguanine-DNA-methyltransferase, a known predictive factor of response to temozolomide in adult-type gliomas), few cases show methylation and potential response to temozolomide." (PMID 39126064, 2024). "In summary, our results indicate that co-administration of temozolomide chemotherapy and mTOR inhibitors reduces temozolomide efficacy via recovery of ROS homeostasis in MGMT promotor methylated glioma cells." (PMID 38182566, 2024). "Glioma patients with MGMT promoter methylation have been shown to respond better to alkylating agent chemotherapy, such as temozolomide, and have improved overall survival compared to those without MGMT promoter methylation." (PMID 39100020, 2024). "In this context, different studies suggested the importance of combined IDH1 and MGMT analysis to predict survival in patients with different types of gliomas." (PMID 38172718, 2024). "The XGBoost algorithm exhibited the best overall performance in predicting glioma grade, IDH mutation status, and MGMT methylation, demonstrating the most balanced score for AUC, sensitivity, and specificity values." (PMID 39100020, 2024). "While GBM shows a clear correlation between MGMT methylation and therapeutic response, these other glial tumors exhibit a nuanced interaction." (PMID 39055560, 2024). "The methylation status of the MGMT promoter in glioma patients has thus emerged as a valuable prognostic biomarker, offering a predictive insight into the tumor’s responsiveness to carmustine therapy." (PMID 39055560, 2024). "The grade of gliomas (P = 0.034, HR 1.737, 95%CI 1.0–2.93) and MGMT expression in immunohistochemistry (P = 0.007, HR 2.211, 95%CI 1.2–3.9) were the independent prognostic factors of PFS." (PMID 39118481, 2024). "We reviewed 26 studies aiming to predict MGMT promoter methylation in patients with glioma based on MRI-radiomic features." (PMID 38308012, 2024). "We explore their value in assessing glioma grade, IDH mutation, 1p/19q codeletion, and MGMT promoter methylation." (PMID 39759149, 2024). "Univariate Cox analysis of survival data indicated that CD13 expression is a high-risk factor for glioma patients like age, grade, and subtype, while IDH mutation, MGMT methylation, and 1p19q codeletion were low-risk factors." (PMID 38519889, 2024). "MGMT (O6-methylguanine-DNA methyltransferase) promoter methylation status is an essential part of molecular diagnostics for all high-grade gliomas (grade 3 and 4)." (PMID 38674436, 2024). "Although less explored, the presence of MGMT methylation in small cell lung cancer indicates a similar mechanism of chemoresistance as observed in gliomas." (PMID 39055560, 2024). "We further categorized these characteristics according to glioma grade, IDH mutation status, and MGMT methylation." (PMID 38167551, 2024). "Our study also found that MGMT promoter unmethylated gliomas typically exhibit higher amide signals." (PMID 39759149, 2024). "Another gene which has been shown to carry prognostic value in gliomas is O6-methylguanine-DNA methyltransferase (MGMT)." (PMID 39272871, 2024). "Our study aims to evaluate the potential of VASARI MRI features in providing accurate and valuable information about glioma characteristics, namely glioma grade, IDH mutation status, and MGMT methylation status." (PMID 38167551, 2024). "Here, we present an epigenetic editing approach using CRISPRoff to introduce site-specific CpG methylation in the MGMT promoter region of glioma cell lines." (PMID 38357209, 2024).
glioma (continued). "Our predictive model demonstrates adequate performance in distinguishing between MGMT-methylated and MGMT-unmethylated gliomas, with an AUC of 0.757." (PMID 38167551, 2024). "Age has been reported as a risk factor for glioma, patients with IDH mutations have a better prognosis, patients with the 1p19q codel have a better prognosis, and MGMT methylated patients are more sensitive to treatment with TMZ." (PMID 38255198, 2024). "Although we failed to achieve a statistically significant association with IDH-mutation and MGMT methylation status, we still found minor differences in APT values according to the molecular profile of gliomas, which influences treatment choices." (PMID 39272871, 2024). "Reciprocally, unmethylated MGMT promoter status leads to an abundance of the MGMT enzyme and is associated with poor response to temozolomide and a decreased survival in patients with GBM and other infiltrating gliomas." (PMID 39273661, 2024). "Of the glioma patients diagnosed and treated at King’s College Hospital, 19.5% had IDH1-mutated tumours and 54.3% were MGMT promoter methylated." (PMID 39767640, 2024). "Veliparib restores sensitivity in TMZ-resistant glioma cells and xenografts and extends survival in the MGMT-hypermethylated GB model, but is ineffective in MGMT-unmethylated lines." (PMID 38473776, 2024). "Another molecular biomarker of glioma subtypes is the methylated form of O6-methylguanine-DNA methyltransferase (MGMT) promoter, which has prognostic, predictive and clinical applications." (PMID 38816839, 2024). "The purpose of this study is to measure the APT signal in different locations of adult-type diffuse gliomas and assess its correlation with glioma grading, molecular profile (IDH-mutation and MGMT promoter methylation status), and survival." (PMID 39272871, 2024). "The most balanced overall performance in predicting glioma grade, IDH mutation status, and MGMT methylation status was achieved by the XGBoost method." (PMID 39100020, 2024). "This multi-institutional, open-label, phase I trial examined a combination of acetazolamide and TMZ in patients with MGMT promoter-methylated high-grade glioma." (PMID 38420615, 2024). "This study underscores the potential of non-invasive VASARI features to predict glioma grading, IDH mutation status, and MGMT methylation, leading to improved patient care." (PMID 38167551, 2024). "VASARI MRI features offer non-invasive and accurate predictive models for glioma grade, IDH mutation, and MGMT methylation status, enhancing glioma patient management." (PMID 38167551, 2024). "Our findings suggest that patient age, Ki-67 labeling index, and VASARI features are significant predictors for glioma grade, IDH mutation status, and MGMT methylation status." (PMID 38167551, 2024). "Cross-validation Least Absolute Shrinkage and Selection Operator (CV-LASSO) logistic regression was applied for statistical analysis to identify significant VASARI features in determining glioma grade, IDH mutation, and MGMT methylation status." (PMID 38167551, 2024). "Patients with hypermethylated MGMT and the IDH1 p.R132H mutation had a better prognosis for their glioma." (PMID 39132504, 2024). "Radiomic features were also used to determine the genetic profiles of ATRX, IDH1/2, MGMT and 1p19q in gliomas." (PMID 38486342, 2024). "Two large‐scale external validations of previous research findings published in 2022 and 2023 also demonstrate that these MRI‐based radiomics models are still insufficient in accurately predicting MGMT in gliomas prior to surgery." (PMID 39252824, 2024). "Our meta-analysis proved that MGMT promoter methylation prediction was less accurate when considering a homogeneous cohort of patients with grade IV gliomas only, whose radiological characteristics are similar." (PMID 38308012, 2024).
glioma (continued). "It has been discovered that methylation of MGMT occurs in 40% of tumors in gliomas and CRC, but only in 25% of tumors in non-small cell lung carcinomas (NSCLCs), lymphomas, and head and neck carcinomas." (PMID 39132504, 2024). "Radiomic prediction of MGMT methylation status showed great heterogeneity of results and lower performances in grade IV gliomas, which hinders its current implementation in clinical practice." (PMID 38308012, 2024). "The presence of 'edema crossing the midline' holds an OR of 0.305 (p = 0.009) in predicting MGMT-unmethylated gliomas." (PMID 38167551, 2024). "According to previous studies, IDH‐wild‐type, MGMT‐unmethylated and mesenchymal subtypes glioma generally exhibit poor prognosis." (PMID 38803199, 2024). "Current prognostic tools for glioma primarily rely on factors such as WHO grade, IDH mutations, 1p/19q codeletion, MGMT promoter methylation, TERT promoter mutations and EGFR amplification." (PMID 39355251, 2024). "After screening multiple glioma cell lines with MSP, western blot analysis and bisulfite sequencing (BiSEQ), we selected LN18 human glioma cells, given the unmethylated MGMT status within target regions of interest and high levels of de novo MGMT expression." (PMID 38224404, 2024). "While the prediction of glioma grade showed promising results, the sensitivity in discerning IDH mutations and MGMT methylation still leaves room for improvement." (PMID 39100020, 2024). "Patients with gliomas in the high‐risk group were associated with high pathologic grade, IDH WT status, MGMT promoter unmethylation, 1p19q non‐codeletion and prone to have a poor outcome." (PMID 39448550, 2024). "In this study, we attempted to create a predictive model from VASARI features to predict glioma grade, IDH mutation status, and MGMT methylation." (PMID 38167551, 2024). "Other investigations have shown that the lncRNA UCA1/miR-182-5p/MGMT axis plays a role in modulating the sensitivity of glioma cells to temozolomide via the MGMT-related DNA damage pathway." (PMID 38255825, 2024). "Patient imaging characteristics varied significantly with glioma grade, IDH mutation, and MGMT methylation." (PMID 38167551, 2024). "It is worth noting that APE1 inhibition would be equally expected to sensitize MGMT-positive gliomas to TMZ." (PMID 39011394, 2024). "CEST-based tumor pH assessment and metabolic profiling demonstrated promising potential for predicting glioma grade, IDH mutation status, 1p/19q codeletion, and MGMT genotype." (PMID 39759149, 2024). "In conclusion, APTw imaging in the solid component provided metrics associated with glioma grade and survival status but showed weak correlation with IDH-mutation and MGMT promoter methylation status, in contrast to previous works." (PMID 39272871, 2024). "The MTR3.5 was the only indicator which can distinguish MGMT promoter methylation and unmethylation gliomas, within MTR3.5 90th percentile performed best (AUC = 0.79, 95% CI: 0.61- 0.91)." (PMID 39759149, 2024). "Among all identified glioma genetic alterations, O6-methylguanine-DNA methyltransferase (MGMT) promoter methylation is an important prognostic molecular marker in clinical settings." (PMID 38308012, 2024). "The most recent systematic review indicates substantial heterogeneity in the results of MRI radiomics models for predicting the methylation status of MGMT in grade IV gliomas, with low performance observed in external validation." (PMID 39252824, 2024). "Few studies have discussed the role of VASARI features in distinguishing between gliomas with methylated and unmethylated MGMT." (PMID 39100020, 2024). "Tissue samples were assessed for glioma grade and underwent molecular testing for IDH mutations and MGMT methylation." (PMID 39100020, 2024). "Expression of MGMT was reported to be lower in tumors such as gliomas, lymphomas, breast cancer, prostate cancer, and retinoblastoma, most likely related to the methylation status of its promoter region." (PMID 38255825, 2024).